TINAG (tubulointerstitial nephritis antigen)
Description:
Mediates adhesion of proximal tubule epithelial cells via integrins alpha3-beta1 and alphaV-beta3. This is a non catalytic peptidase C1 family protein.
Synonyms: TIN-Ag
Tractability: Antibody: UniProt places it where antibodies can reach, with high confidence; its Gene Ontology location is reachable by antibodies, with medium confidence.
Gene: Protein-coding gene on chromosome 6 (54,307,859 to 54,390,142, forward strand). Ensembl gene ENSG00000137251.
Subcellular location: Secreted, extracellular space, extracellular matrix, basement membrane
Gene Ontology:
Molecular function: cysteine-type endopeptidase activity; nucleotide binding; cysteine-type peptidase activity
Biological process: cell adhesion; proteolysis
Cellular component: basement membrane; lysosome
Genetic constraint (gnomAD): Loss-of-function variants: 62 observed, 56.22 expected, observed/expected ratio (o/e) 1.1, 90% interval 0.9 to 1.36. The upper end of that interval is the gene's LOEUF score, 1.36, which puts it in group 5 of 6, group 1 being the genes least tolerant of losing a copy. Missense variants: 615 observed, 515.66 expected, observed/expected ratio (o/e) 1.19, 90% interval 1.12 to 1.27. Synonymous variants: 212 observed, 177.77 expected, observed/expected ratio (o/e) 1.19, 90% interval 1.07 to 1.34.
Homologues: Orthologues: chimpanzee TINAG (99% identical), macaque TINAG (95% identical), pig TINAG (89% identical), rabbit TINAG (86% identical), mouse Tinag (86% identical), rat Tinag (85% identical), guinea pig TINAG (84% identical), dog TINAG (80% identical), zebrafish tinagl1 (47% identical), Caenorhabditis elegans F26E4.3 (36% identical), Drosophila melanogaster Swim (20% identical), Caenorhabditis elegans cpr-4 (18% identical), and 16 more. Paralogues in human: TINAGL1 (46% identical), CTSC (20% identical), CTSZ (17% identical), CTSB (16% identical), CTSH (14% identical), CTSK (14% identical), CTSL (14% identical), CTSV (14% identical), CTSO (13% identical), CTSS (13% identical), CTSW (12% identical), CTSF (12% identical).
Diseases named in the same sentence as TINAG in open-access papers:
TINAG is named in the same sentence as 16 diseases in open-access papers, as found by Europe PMC text mining. Sharing a sentence is not in itself a finding about the gene and the disease. The quoted sentences say what the papers report.
nephritis (5 papers, 2010 to 2017). Inflammation of renal tissue. "Among all imputed markers associated with severe diabetic retinopathy at a P-value less than 10−4, there are 7 SNPs located in 6p11-12 where TINAG (tubulointerstitial nephritis antigen) is encoded." (PMID 20871662, 2010). "The closest gene to the significant SNP on BBC23 (AX-85048470) is tubulointerstitial nephritis antigen (TINAG), a gene involved in immune response." (PMID 28981529, 2017). "A major component of the vascular BMs was tubulointerstitial nephritis antigen, TINAG, a BM protein that had previously been identified in kidney tubular BMs (16.7%)." (PMID 29284024, 2017). "The top 5 up-regulated genes based upon fold change between groups were: carbamoyl-phosphate synthase 1 (CPS1), carboxypeptidase O (CPO), tubulointerstitial nephritis antigen (TINAG), solute carrier family 7, member 9 (SLC7A9), and solute carrier family 6, member 19 (SLC6A19)." (PMID 27093613, 2016).
tubulointerstitial nephritis (5 papers, 2020 to 2025). "TINAG is a protein-coding gene, and diseases associated with TINAG include membranous nephropathy and interstitial nephritis." (PMID 39596629, 2024). "The 26-Mb QTL region on SSC7 was also detected for cNurHScore (1.2% of genetic variance) and harbors the TINAG gene, which encodes a basement membrane glycoprotein that was initially identified as a target of antibodies in some forms of immunologically mediated tubulointerstitial nephritis." (PMID 35100362, 2022). "The expression of TINAG has been reported to be related to the development of kidney-related diseases, such as membranous nephropathy, interstitial nephritis, obstructive nephropathy, and renal clear cell carcinoma." (PMID 41551156, 2025). "TINAG is a protein-coding gene coding a basement membrane glycoprotein initially identified as a target of antibodies in some forms of immunologically mediated tubulointerstitial nephritis." (PMID 35268332, 2022). "Notably, the mix of ADAMTS5-affected matrix proteins was enriched in basement-membrane components including laminins (LAMA/LAMB/LAMC), collagen-6 (COL6A1/A2), collagen-12 (COL12A1), AGRN, nidogen-1 (NID1), and TINAG (tubulointerstitial nephritis Ag)." (PMID 32917786, 2020).
pancreatic cancer (3 papers, 2017 to 2025). "Moreover, TINAG can promote cell proliferation of pancreatic cancer, serving as a prognostic indicator for this cancer." (PMID 41551156, 2025). "Along with six other top DEGs, i.e. TINAG, LINC00460, UGT1A9, SLCO1B7, HOTTIP, and ALCO1B3, their expression status could not be found in the Pancreatic Cancer Database." (PMID 28418924, 2017).
diabetic retinopathy (1 paper, 2010). "There were 32 SNPs associated with severe diabetic retinopathy at P-value less than 10−4, with 7 of these top signals in chromosomal region 6p11-12, where tubulointerstitial nephritis antigen (TINAG) is encoded." (PMID 20871662, 2010).
glaucoma (1 paper, 2023). Increased pressure in the eyeball due to obstruction of the outflow of aqueous humor. "Of the most significant coding variants identified by MPR80 following Bonferroni correction, only one SNP, rs3195579 (TINAG), was found to be associated with protection or lower risk of glaucoma medication non-adherence." (PMID 36982708, 2023).
hand (1 paper, 2023). "The dysregulation of TINAG gene expression has previously been associated with hand OA." (PMID 36983761, 2023).
nephronophthisis (1 paper, 2021). Progressive tubulointerstitial injury, inherited in an autosomal recessive pattern, caused by mutations in genes involved in ciliary function, which may result in an end stage renal failure. "Mutation of the TINAG gene is involved in nephronophthisis via influencing cell survival." (PMID 34630525, 2021).
cancer (4 papers, 2019 to 2026). A tumor composed of atypical neoplastic, often pleomorphic cells that invade other tissues. "Through a literature search, we found that TINAG plays a major role in regulating kidney-related diseases; however, there are few studies on cancer." (PMID 37214471, 2023).
kidney disease (2 papers, 2019 to 2024). "Using a lower threshold (p < 0.05), genes previously linked to kidney disease (TINAG and COL4A1) were found among common risk genes." (PMID 38767678, 2024).
tumor (2 papers, 2021 to 2024). "Decreasing RNA expression levels of NAT8, TINAG, and SLC17A1 were associated with lower tumor grade of KIRC." (PMID 34630525, 2021). "Increased expression of TIMP1, MMP1, AGRN, UNC5A, and ADAMTS4 was observed, while the expression of UNC5C, TINAG, SPOCK3, and ITGA7 was reduced in the normal FHC cells compared to the HCT8 tumor cells." (PMID 39011483, 2024). "Meanwhile, a higher tumor T stage was accompanied by reductions of RNA expression levels of NAT8, TINAG, and SLC17A1." (PMID 34630525, 2021). "DNA methylation levels of NAT8, TINAG and SLC17A1 was accompanied by an increasing tumor T stage." (PMID 34630525, 2021).
TINAG also shares sentences with these, for which no sentence is quoted: membranous nephropathy (2 papers); diabetes (1); hand osteoarthritis (1); hepatocellular carcinoma (1); Pectus excavatum (1); renal clear cell carcinoma (1).